ZNF500 (zinc finger protein 500)
Description:
May be involved in transcriptional regulation.
Synonyms: KIAA0557; ZKSCAN18; ZSCAN50
Tractability: No criterion of Open Targets' tractability assessment is met for any kind of drug.
Gene: Protein-coding gene on chromosome 16 (4,748,239 to 4,767,624, reverse strand). Ensembl gene ENSG00000103199.
Subcellular location: Nucleus
Subcellular location (Human Protein Atlas): Nucleoplasm; Cytosol
Pathways (Reactome):
Gene expression (Transcription): Generic Transcription Pathway
Gene Ontology:
Molecular function: protein binding; DNA-binding transcription factor activity, RNA polymerase II-specific; RNA polymerase II cis-regulatory region sequence-specific DNA binding
Biological process: regulation of transcription by RNA polymerase II; regulation of DNA-templated transcription
Cellular component: cytosol; nucleoplasm; nucleus
Genetic constraint (gnomAD): Loss-of-function variants: 31 observed, 31.5 expected, observed/expected ratio (o/e) 0.98, 90% interval 0.74 to 1.33. The synonymous counts are far from expectation, so gnomAD's model fits this gene poorly and the ratio says little. Missense variants: 817 observed, 642.31 expected, observed/expected ratio (o/e) 1.27, 90% interval 1.2 to 1.35. Synonymous variants: 392 observed, 273.73 expected, observed/expected ratio (o/e) 1.43, 90% interval 1.32 to 1.56.
Homologues: Orthologues: chimpanzee ZNF500 (99% identical), macaque ZNF500 (94% identical), dog ZNF500 (71% identical). Paralogues in human: ZNF263 (37% identical), ZNF397 (34% identical), ZSCAN25 (34% identical), ZNF213 (33% identical), ZKSCAN8 (33% identical), ZNF394 (33% identical), ZSCAN30 (33% identical), ZKSCAN1 (33% identical), ZKSCAN3 (32% identical), ZKSCAN4 (32% identical), ZSCAN12 (32% identical), ZSCAN22 (32% identical), and 18 more.
Diseases named in the same sentence as ZNF500 in open-access papers:
ZNF500 is named in the same sentence as 1 disease in open-access papers, as found by Europe PMC text mining. Sharing a sentence is not in itself a finding about the gene and the disease. The quoted sentences say what the papers report.
breast carcinoma (1 paper, 2024). "But literature verification found that ZNF500 suppressed breast cancer cell proliferation, and enrichment analysis found that it was enriched in breast cancer related cell line MCF7." (PMID 39095659, 2024). "Six breast cancer differentially localized proteins were got: CCNT1, NSUN5, PRPF4, RECQL4, UTP6, ZNF500." (PMID 39095659, 2024).